HLA-B (major histocompatibility complex, class I, B)
Diseases named in the same sentence as HLA-B in open-access papers (continued):
Sharing a sentence is not in itself a finding about the gene and the disease.
Behçet’s disease (38 papers, 2007 to 2026). "The HLA-B*51 allele is considered the risk factor for Behçet’s disease, a disease that has a strong geographical prevalence distribution along the ancient Silk Road which ran from the Mediterranean to Northern China58." (PMID 35504942, 2022). "Peptides eluted from HLA-B*51, the main risk allele of Behçet’s disease, accounted for approximately 25% of the HLA-B*51 peptidome." (PMID 36700227, 2022). "More recently, a robust genetic association between a genetic variant between HLA-B and MICA was suggested to explain the association with HLA-B*51 in Behçet's disease." (PMID 33644100, 2021). "It is also likely that a haplotype effect that includes both coding and non-coding genetic variants within the HLA-B region is involved in Behçet's disease." (PMID 33644100, 2021). "The association of the classical allele HLA-B*51 is well-established and is considered the strongest genetic risk factor for Behçet's disease." (PMID 33644100, 2021). "Behçet’s disease (BD), a multi-organ inflammatory disorder, is associated with the presence of the human leukocyte antigen (HLA) HLA-B*51 allele in many ethnic groups." (PMID 26331842, 2015). "HLA-B*51 and HLA-B*15 alleles have been associated with Behcet disease, B*44, B*51, B*57, B*15 with HPV infection and protection/susceptibility to in cervical carcinoma." (PMID 17480220, 2007). "In the clinical context of the new medical concept of diseases related to the Major Histocompatibility Complex class I (MHC-I-opathy), contrasting data are available on the possible association among HLA-B*51, Behcet's disease (BD), and spondyloarthritis (SpA)." (PMID 42123313, 2026). "The HLA-B*51 allele is associated with an increased susceptibility for developing Behcet’s disease." (PMID 39201523, 2024). "The implications of the HLA-B*51 allele in the development of Behcet disease are still yet to be fully understood, while the involvement of the HLA-B*18:01 variant in antitumor immune response needs much more research and comprehension and HLA-B*35 alleles have no yet determined correlations." (PMID 39201523, 2024). "Studies investigating the association between HLA-B*51 and Behçet’s disease." (PMID 38003572, 2023). "It is interesting to note that one of the predisposing factors, HLA-B*57, is also associated with Behcet’s disease, a systemic vasculitis of unknown etiology, characterized by damage to vessels of any size or type." (PMID 36360904, 2022). "On the other hand, this study consider the impression of other HLA-B alleles (“HLA-B27”) on the risk of BD and the reinforcement of hypothesis Behcet disease–gene association." (PMID 30891643, 2019). "The strongest genetic risk factor of Behçet’s disease (BD) is HLA-B*51." (PMID 30872678, 2019). "Behçet’s disease (BD) as systemic vasculitis of unknown etiology is associated with HLA-B*51 in European and Asian populations." (PMID 24887019, 2014). "However, they are associated with two different vasculitides (HLA-B*51 in Behçet's disease and HLA-B*52 in Takayasu's arteritis (TAK)) and with major clinical and immunological differences." (PMID 22309845, 2012). "However, whether the classical allele HLA-B*51 or the HLA-B/MICA intergenic locus is causal in Behçet's disease requires further investigation." (PMID 33644100, 2021). "According to genome wide association (GWA) studies as well as candidate gene approaches, Behçet’s disease (BD) is associated with human leukocyte antigen (HLA)-A and HLA-B gene regions." (PMID 24286189, 2013). "The prevalence of HLA-B*51 in this population was also lower than previously reported prevalence in geographically similar patients with Behçet’s disease." (PMID 37865787, 2023). "Examples of associations between certain HLA types and autoimmune disease include HLA-B*27 and spondyloarthritis (SpA), HLA-B*51 and Behcet’s disease, and HLA-DRB1*15:01 and multiple sclerosis." (PMID 30772894, 2020).
Behçet’s disease (continued). "The precise role of HLA-B*51 in Behçet's syndrome remains uncertain, with ongoing debates about whether it is directly involved in the disease or merely acts as a marker." (PMID 38575661, 2024). "Although Behçet’s disease has not been found to be associated with autoantibodies, it is related to the HLA-B*51 allele of the class I MHC, and infectious triggers have been observed." (PMID 37865787, 2023). "HLA-B*51 and ERAP1 affect the risk of developing Behçet's disease (BD)." (PMID 32161166, 2020). "Finally, a recently published analysis of imputed genome wide association study data described an association between a genetic variant located between the HLA-B and MICA loci and Behçet’s disease." (PMID 25889603, 2015). "However, in these studies a relationship between HLA-B*51 and Behçet's disease was also reported, suggesting that the observed association between MICA*009 and Behçet's disease arises from a strong linkage disequilibrium with HLA-B*51." (PMID 25838620, 2015). "In this context, the aim of this study was to better characterize the risk conferred by HLA-B alleles and MHC SNPs for Behçet’s disease in an Iranian dataset and to test if there is a correlation between the genotypes at the strongest genetic risk factors and characteristics of BD patients." (PMID 25889189, 2015). "The HSV-induced Behcet's syndrome is more common in individuals expressing HLA-B*51." (PMID 21829673, 2011). "Behçet's syndrome is a rare, systemic inflammatory vascular disorder with unknown etiology, although associations with HLA-B*51 and several non-MHC loci including IL23R-IL12RB2 and IL-10 have been described." (PMID 33996677, 2021).
cervical carcinoma (28 papers, 1994 to 2025). A carcinoma arising from either the exocervical squamous epithelium or the endocervical glandular epithelium. "A study from South India reported that HLA B*07 was the most common allele (6–13%) in the HLA-B gene, and its association with cervical cancer along with HLA DQ8 was found to be significant." (PMID 34442381, 2021). "Studies have reported that the haplotype HLA‐B*0702‐DRB1*1501/HLADQB1*0602 increases the risk of cervical carcinoma, whereas the haplotype HLA‐B*1501/HLA‐DRB1*1301/HLA‐DQA1*0103/HLA‐DQB1*0603 protects from the risk of the disease progression." (PMID 33586351, 2021). "Consistent with the weak HLA-B*15 association with HPV18-associated cervical cancer, only marginal association was seen in this group with position 156 in HLA-B (P = 0.014)." (PMID 28806749, 2017). "Recent cervical cancer sequencing studies have demonstrated a high carriage rate of deletions involving HLA-B providing further evidence that HLA-B is directly involved in cervical cancer risk or pathogenesis." (PMID 28806749, 2017). "Notably, seven patients in the present study carried the probable oncogenic germline mutation in HLA-B, a well-known cervical cancer susceptibility gene." (PMID 35205332, 2022). "For example, the HLA-B c.A161G variant, which was detected in 9 patients (3.1%) here, was also found to be associated with high-grade cervical preinvasive lesions and invasive cervical cancer in a recent genome-wide association study." (PMID 36424660, 2022). "This genetic association study uses fine mapping of the major histocompatibility complex (MHC) region by human leukocyte antigen imputation to determine whether the HLA-B*52:01 allele is associated with cervical cancer (CC) in Japanese women." (PMID 33119109, 2020). "Once mutational profiles of sufficient tumours of different histological type are reported, it will be interesting to use this data to test the hypothesis that HLA-B mutations differentially predispose to different histological types of cervical cancer." (PMID 28806749, 2017). "In addition, there was more complete HLA-A loss in SCC metastasis, while there was more complete loss of HLA-B/C in AC metastasis, again emphasizing the need for better immune-characterization of the two major cervical cancer histological subtypes." (PMID 27895918, 2016). "The nearby HLA-B*0702 has been reported to be associated with cervical cancer risk 5,43,44." (PMID 24403192, 2014). "Strong associations between HPV16 cervical cancer cases and amino acid positions 13 and 71 were found in HLA-DRB1 (P = 2.69 × 10−13 and 6.22 × 10−7 respectively), and position 156 in HLA-B (P = 4.93 × 10−8)." (PMID 28806749, 2017). "A GWAS of cervical cancer (CIN2, CIN3 and cervical cancer) based on patients of mixed European descent identified associations with both HLA-B*07 and HLA-B*15:01 and squamous cervical cancer (personal communication)." (PMID 27285765, 2016). "The intention of our study is to highlight that screening for HLA-B*15∶02 has the potential to be a worthwhile health strategy like screening for breast and cervical cancer, with comparable efficiency and cost-efficiency." (PMID 24806465, 2014). "It was previously demonstrated that knocking out the IFITM1 and IFITM3 proteins led to the downregulation of HLA-B expression on the surface of cervical cancer cells, suggesting an explanation for the inverse correlation between IFITM1/3 expression and metastasis formation." (PMID 40314078, 2025). "Specifically, three haplotypes, HLA-DRB1*15/HLA-DQB1*0602/HLA-DQA1*0102, HLA-B*0702/HLA-C*0702 and HLA-DRB1*0401/HLA-DQA1*0301, were associated with increased risk of both HPV16 and HPV18-associated cervical cancer, and for the development of both squamous cell carcinoma and adenocarcinoma." (PMID 34683414, 2021).
cervical carcinoma (continued). "Overall, three haplotypes, HLA-DRB1*15/HLA-DQB1*0602/HLA-DQA1*0102, HLA-B*0702/HLA-C*0702, and HLA-DRB1*0401/HLA-DQA1*0301, were associated with increased risk of both HPV16 and HPV18-associated cervical cancer, and for the development of both squamous cell carcinoma and adenocarcinoma." (PMID 28806749, 2017). "Variation in LD between the classic HLA loci, rs9272143 and rs67841474 between populations may explain the different associations of HLA-B*07 and DRB1*1501-DQB1*0602 with cervical cancer between studies." (PMID 24520070, 2014). "Additionally, both HLA-A and HLA-B interacted with PIK3CA, which were reported to confer radioresistance to cervical cancer, suggesting that HLA-A and HLA-B may also be involved in radiotherapeutic resistance of cervical cancer." (PMID 35205332, 2022). "Another study conducted in Europe, including a total of 2866 cervical cancer cases and 6481 controls confirmed the strong association of the MHC with cervical neoplasia, and identified the amino acid positions 13 and 71 in HLA-DRB1 and 156 in HLA-B (within both HLA Class I and Class II alleles)." (PMID 34683414, 2021). "Considering HPV18-associated cervical cancer (n = 166 cases), association with increased risk was strongest with HLA-DRB1*15 (OR = 1.68, P = 0.0013) and HLA-DQB1*0602 (OR = 1.65, P = 0.0030), with only nominal HLA Class I risk associations seen with HLA-B*0702 and HLA-C*0702." (PMID 28806749, 2017). "In order to investigate whether these changes are associated with biological behaviour of the tumours, 20 cervical carcinomas were analyzed for MHC (HLA-A, HLA-B/C, HLA-DR) and TAP-1 expression in the primary tumours and in lymph node metastases by immunohistochemistry." (PMID 8198988, 1994). "They described a protein–protein interaction between HLA-B and the IFITM1/3 proteins in the SiHa cervical cancer cell line, and IFITM1/3 knockout was shown to lead to HLA-B downregulation." (PMID 36466909, 2022). "Remarkably, expression of HLA‐A, HLA‐B, and HLA‐C was significantly lower in NEC‐GYN compared to ovarian and cervical cancer (P‐value < 0.0001), further corroborating immunosuppressive nature of NEC‐GYN." (PMID 34245124, 2021). "We analyzed the Illumina HiSeq RNA expression data from the TCGA head & neck squamous cell carcinoma (HNSC) and cervical carcinoma (CESC) cohorts for expression of HLA-A, HLA-B, and HLA-C, the three classical genes." (PMID 28891951, 2017). "Classical (HLA-A and HLA-B/C)- and non-classical HLA molecules (HLA-E and HLA-G) were studied on primary tumors and paired lymph node (LN) metastases from cervical cancer patients (n = 136) by immunohistochemistry." (PMID 27895918, 2016). "In pancreatic cancer, HLA‐B modulates ITGB1 expression, influencing migration and transmembrane signaling, while its altered expression impairs tumor antigen recognition in cervical cancer and affects immune checkpoint inhibitor efficacy in gastrointestinal malignancies." (PMID 41316520, 2025). "Notably, the genotype HLA-B*15 (HLA Class I) was strongly associated with reduced risk of squamous cell carcinoma and HPV16-associated cervical cancer but was not linked to HPV18-associated cervical cancer." (PMID 34683414, 2021). "In the present study, it was confirmed that, in addition to HLA-B, IFITM1 regulates a whole set of surface proteins in cervical cancer cells, both with and without dependence on IFNγ." (PMID 40314078, 2025).
spondyloarthritis (28 papers, 2013 to 2026). "Spondyloarthritis (SpA) shares immunogenetic and clinical overlaps with BD, notably through associations with HLA class I alleles, particularly HLA-B*27." (PMID 41900928, 2026). "The landscape of non-HLA-B*27 associations in spondyloarthritis is notably shaped by population-specific genetic architectures." (PMID 40806743, 2025). "Studies carried out on spondyloarthropathy suggest that the Face-2 dimerization is caused by Cysteine67 residues in the α-domain of the HCs of HLA-B alleles." (PMID 37627243, 2023). "Heritability of Spondyloarthritis (SpA) is highlighted by several familial studies and a high association with the presence of human leukocyte antigen (HLA)-B*27." (PMID 33763060, 2021). "Due to the high HLA polymorphism and the differentiated contribution of alleles and molecules encoded by them, HLA-B*27 allele identification is relevant in the clinical follow-up, diagnosis, and treatment of this spondyloarthropathy." (PMID 33146354, 2020). "HLA-DRB1*0103, HLA-B*27 and HLA-B*58 are associated with erythema nodosum, spondylarthropathy and uveitis." (PMID 30682031, 2019). "It must also be considered that this same feature, through the yield of unstable peptide:HLA complexes, would fuel the tendency of the HLA-B*2705 to produce aberrant forms implicated in the pathogenetic mechanisms of the associated Spondyloarthritis." (PMID 31212633, 2019). "Despite the strength of this association, mechanisms accounting for the link between HLA-B*27 and spondyloarthritis remain a mystery." (PMID 29675414, 2018). "More than four decades ago, major histocompatibility complex (MHC) class I allele group HLA-B*27 was identified as a potent risk factor for developing spondyloarthritis." (PMID 29675414, 2018). "In studies of patients of Northern European descent, HLA-B*2705 is the most frequently associated with AS and related spondyloarthropathies, which include AAU." (PMID 28124984, 2017). "Conversely, HLA-B*57 predisposes to immune over-activation syndromes, e.g. abacavir hypersensitivity (HLA-B*5701) and spondylarthropathies (HLA-B*5703)." (PMID 26241854, 2015). "Additionally, the distinct peptide-binding repertoires observed within the risk allele cluster (HLA-B*08, B*18, B*35, B*40, and B*54) implicate distinct immunopathogenic mechanisms in spondyloarthritis." (PMID 40806743, 2025). "Association of HLA-B*27 and various classes of Spondyloarthritis." (PMID 33763060, 2021). "It is likely that a combination of these hypotheses, with HLA-B*27 taking center stage, will eventually explain the development of spondyloarthritis in predisposed individuals." (PMID 33092023, 2020). "The HLA-B*27 allele group is the strongest genetic risk factor for spondyloarthritis." (PMID 29675414, 2018). "These patterns may reflect underlying linkage disequilibrium structures within the HLA class I region, suggesting that certain extended haplotypes, involving both MICA and HLA-B alleles, could also contribute to genetic susceptibility or modulation of disease phenotype in spondyloarthritis." (PMID 40806743, 2025). "Considering the marked differences in the peptide-binding patterns of HLA-B*27 compared to the other risk alleles identified in this study, it is highly likely that distinct pathogenic mechanisms are involved in HLA-B*27-associated versus B*27-negative spondyloarthritis." (PMID 40806743, 2025). "The interpretation of Hardy–Weinberg disequilibrium (HWD) data for HLA-B genotypes in HLA-B*27-negative spondyloarthritis patients requires caution due to several potential confounding factors." (PMID 40806743, 2025). "Full HLA typing was not a routine procedure for RA patients in Croatia, but sometimes we had ordered the data for the HLA-B locus to exclude the peripheral type of HLA-B27 + spondyloarthritis." (PMID 41325321, 2025). "Our study presents the first detailed immunogenetic characterization of an HLA-B*27-negative spondyloarthritis cohort from Romania." (PMID 40806743, 2025).